AR (androgen receptor)
Diseases named in the same sentence as AR in open-access papers (continued):
Sharing a sentence is not in itself a finding about the gene and the disease.
tumor (continued). "In our study, we investigated whether the increased AR signaling induced by over-expression and treatment with an exogenous androgen could dampen the NK cell killing efficiency against tumor cells by upregulating the classic immunosuppressive molecule PD-L1." (PMID 35915245, 2022). "Moreover, we analyzed the proliferative index in tumor sections and found that the expression levels of Ki-67, a marker of proliferation, and AR were much lower in ATF4-overexpressing xenograft mice than in the control xenograft mice." (PMID 35013318, 2022). "Furthermore, LAR tumours and cell line models display high dependencies on AR, FOXA1, ERBB2, and AKT protein and phospho-protein signalling, as well as frequent PIK3CA and ERBB2 mutations." (PMID 36077812, 2022). "However, AR was negatively related to the tumour stage and was identified as a well‐described prognostic factor in conventional RCC types." (PMID 35452181, 2022). "Estrogen receptor (ER) and Androgen receptor (AR) are frequently co-expressed in BC, although they may behave in different ways in view of the tumor heterogeneity." (PMID 35057779, 2022). "A greater understanding of the LAR group has led to the ongoing evolution of therapeutic combinations, including those of AR inhibitors with PI3K inhibitors given the frequent co-amplification of PIK3CA in AR-positive tumours, which is estimated to be as high as 40%." (PMID 35877237, 2022). "However, high expression levels of AR, especially a high AR to ERα nuclear staining ratio (AR:ERα) in tumor cells, can result in resistance to endocrine therapy." (PMID 36450882, 2022). "This reduced in vivo tumour growth indicating that ARLNC1 may be a viable therapeutic target in AR-dependent PCa." (PMID 35159022, 2022). "In addition, owing to the effective tumor targeting, mice treated with Di-PP/AR-siRNA/DTX displayed a higher rate of anti-tumor efficacy than PP/AR-siRNA/DTX (p < 0.05), as expected." (PMID 35631549, 2022). "The questions remain whether an AR-positive CRPC tumour is driven by the AR signalling, or it is AR indifferent and other oncogenic pathways replace AR to promote tumour progression." (PMID 35832549, 2022). "As expected, mutations in the AR and DNA repair genes included in our panel were the most common ones, in particular, the ATM and BRCA1/BRCA2 genes, and they seemed to drive high tumor mutation load and rapid polymetastatic spread after the first oligorecurrence treated with SBRT." (PMID 35740343, 2022). "While those results need to be further evaluated with newer AR inhibitors, they suggest that combining HADCs and AR inhibitors may be an effective strategy to re-sensitize tumours to AR inhibition." (PMID 35205419, 2022). "Based on these findings from cell models, we can speculate that AR target therapy will only provide short-term tumour suppression." (PMID 35832549, 2022). "However, in recent years, it has become more prevalent for NEPC occurrence in CRPC patients who have received potent AR signaling inhibitors, which trigger the AR-independent tumor growth and neuroendocrine differentiation." (PMID 36159187, 2022). "Consequently, ARPIs cannot inhibit tumor growth because tumors lose their dependence on AR signaling." (PMID 35938167, 2022). "Au‐AR pep‐PROTAC accumulated within the tumor obviously and could be eliminated in organs after 72 h." (PMID 35971165, 2022). "It is important to differentiate tumours by various modes of action of AR so that effective ARPI treatments could be used." (PMID 35832549, 2022). "Thus, we proposed that CIC mainly promotes PCA development and progression through indirect mechanisms, such as androgen receptor (AR), epithelial-mesenchymal transition and the tumor microenvironment." (PMID 35154101, 2022). "Furthermore, immunohistochemical staining of tumor tissues revealed that the expression of PD-L1 was decreased by targeting AR with Enz." (PMID 35915245, 2022). "DCEM1 downregulates c-Myc, EZH2, and AR as well as inhibits tumor growth in vivo." (PMID 35653190, 2022).
tumor (continued). "However, the role of AR mediated gene repression in PCa progression and treatment is complex as the AR has been shown to also directly repress tumor suppressor genes such as DEPTOR, E-cadherin, c-Met, and GPER1." (PMID 35018219, 2022). "This study may refer to the influence of AR on the tumor immune microenvironment and provide a potential approach to target this newly identified pathway to better suppress BCa progression." (PMID 35915245, 2022). "Despite mounting evidence of the pervasive influence of ZIC5 in multiple cancer types, the association between ZIC5 and AR signaling or with PCa tumor aggressiveness has not been fully defined." (PMID 36127329, 2022). "Since Src had been demonstrated to contribute to tumours developing resistance to AR target therapy, a phase II trial was also designed to test 26 metastatic CRPC patients with no prior chemotherapy who received abiraterone plus prednisone together with placebo or dasatinib." (PMID 35832549, 2022). "AR signaling in EC has both oncogenic and tumor suppressive effects, which may depend on the different stages of EC." (PMID 36358974, 2022). "Indeed, a recent study clarified that the AR agonist/AR signaling pathway has a tumor suppressor role in ER-positive BRCA." (PMID 35880165, 2022). "Therefore, the level and activity of various MAPK proteins can be modulated not only by the AR inhibition but also as a function of tumour progression." (PMID 35326402, 2022). "Given the regulation of UGT2B28 expression by AR, we sought to determine whether the organoid formation and tumor growth phenotypes that we observed in AD cell lines in response to UGT2B28 manipulation were dependent on androgen-bound AR signaling." (PMID 35954173, 2022). "Given that both immunotherapy and AR inhibitors interfere with tumour growth and proliferation, it is thought that they could have synergistic effects leading to better disease control." (PMID 35877237, 2022). "We also wanted to see how conditions in specific tumor structures affect AR expression." (PMID 36361793, 2022). "AR is known to play a role in tumor cell metabolic reprogramming during PCa progression." (PMID 36358940, 2022). "The dual roles of PARP in DNA damage response and sustaining AR function taken in conjunction with data showing that abrogating AR signalling induces an “HRR-deficient” phenotype provide the basis for co-targeting AR and PARP concurrently to slow down tumour proliferation and disease progression." (PMID 36497408, 2022). "Similarly, the distribution of AR was bimodal with a broad peak at > 60% of tumor cells staining positive for AR, and another peak at < 10%." (PMID 36527133, 2022). "Furthermore, concomitantly treating CRPC cells with the abiraterone and ErbB2 inhibitor, lapatinib, blocked AR reactivation and suppressed tumor progression." (PMID 35645241, 2022). "By further research on the pathogenesis of CRPC, it is found that AR available to drive tumor progression is still the key factor to promote the occurrence and development of CRPC, therefore, androgen deprivation therapy remains the basic means to control the occurrence and development of CRPC." (PMID 35594510, 2022). "If AR-downmodulation in the stroma drives proliferation and dedifferentiation of tumor epithelial cells or if dedifferentiated and proliferating epithelial cells lack the ability to maintain a differentiated AR+ stroma smooth muscle cell phenotype remains to be explored." (PMID 36358614, 2022). "Several anticancer drugs target androgen receptor signaling to prevent tumor growth." (PMID 34570813, 2021). "In addition, the SPOP protein plays a role as a tumor suppressor that negatively regulates the stability of multiple other oncogenic substrates in PrCa, including AR, SRC-3, c-MYC, ERG, DEK, BRD4 and Trim24." (PMID 34857003, 2021).
tumor (continued). "In this review, the interaction between AR signaling and other molecular pathways involved in tumor pathogenesis and its clinical implications in metastasis and advanced disease will be discussed, along with a thorough overview of current and ongoing novel treatments for AR signaling inhibition." (PMID 33805919, 2021). "Indeed, these cancer stem cells (CSCs), also known as tumor-initiating cells, are AR-independent and commonly maintained into the hypoxic tumor microenvironment." (PMID 34103085, 2021). "The anti-tumor effect of AR has been widely concerned by scholars at home and abroad." (PMID 34887934, 2021). "The effects of LINC00667 silencing in cell proliferation, cell migration, and cell invasion, and androgen receptor (AR) expression were determined with loss-of-function phenotypic analysis in Huh-7 and HCCLM3 cells, and subsequently testified in vivo in tumor growth." (PMID 34907204, 2021). "Qi Xiaoxiao found that at the dose of (100 g/L), the intragastric administration of AR could slow down the growth of the tumor, and the tumor inhibition rate was 34.7%." (PMID 34887934, 2021). "Based on the theory that the proliferation and survival of most PCa cells depend on the androgen signaling pathway, previous efforts have revealed the role of restored AR signaling (such as increased testosterone levels within the tumor), AR bypass signaling, and complete AR independence in CRPC." (PMID 35096586, 2021). "KLK3, AZGP1 and PIP are AR regulated and reflect tumor AR activity." (PMID 34736512, 2021). "AR overexpression results in tumor growth despite minimal androgen stimulation." (PMID 34771580, 2021). "Importantly, EPI derivatives were capable of inhibiting the AR and reducing tumour burdens in animal models and entered a small-scale phase I/II clinical trial as EPI-506 (ralaniten) in 2016 (NCT02606123)." (PMID 33572755, 2021). "PRAD and BLCA are primarily related to the regulation of androgens and their receptors, and inhibiting androgen receptor signaling and androgen deprivation therapy are well established to restrain tumor cell biological behaviors and provide patients with benefits in prolonging the recurrence period." (PMID 34869761, 2021). "NEPC, that is characterized by low expression of AR, could be developed from AR-positive tumor by lineage plasticity induced by transcriptional programs." (PMID 34145268, 2021). "However, it has to be mentioned that information from the literature regarding this interplay between PSMA and AR and its effect on tumor growth is heterogeneous, and we have to conclude that the mechanism is not yet fully understood." (PMID 34298770, 2021). "Inflammatory cytokines secreted within this activated tumor microenvironment may further amplify these redox signaling networks and crosstalk with the AR signaling pathway, to enable a persistent mitogenic activation of PCa cells and the selection of CRPC." (PMID 35582006, 2021). "The inhibitory effects of the AR antagonist are dose-dependent with 80 μM enzalutamide exhibiting a significantly enhanced effects suppressing tumor sphere formation/CSC subpopulation in U87MG cell line compared with the negative control or lower concentration of enzalutamide (40 μM)." (PMID 34094902, 2021). "This study suggests that the profiling of tumor-based interaction between AR, ki67, VEGF, HIF1beta and MMP9 in epithelium and stroma may be a significant contribution in the personalized diagnostics of OSSC." (PMID 33920263, 2021). "Although androgen-deprivation therapies and/or the administration of first-generation competitive AR inhibitors prevent further tumor growth for a while, most patients develop resistance to the treatment and subsequently progress to castration-resistant prostate cancer (CRPC)." (PMID 33420371, 2021).
tumor (continued). "In PCa, activation of the PI3K/AKT pathway promotes the nuclear translocation of β-catenin, which triggers the expression of proliferation and EMT-related genes and specifically promotes tumor progression by transactivating androgen receptor and its downstream pathway." (PMID 34249931, 2021). "Thus, the miR-185 has been suggested as a negative regulator of AR signaling and tumor suppressor miRNA in LNCaP cells." (PMID 34831421, 2021). "Given the functional overlap between these tumor suppressors and oncogenes, it is conceivable that various combinations in concert may induce lineage plasticity from AR-positive to AR-negative disease." (PMID 33420371, 2021). "A heterogeneous population of AR‐positive and AR‐negative tumour cells was observed." (PMID 33797847, 2021). "Interestingly, all fish went on to develop HCC, indicating that the tumorigenic role of androgen-receptor signalling is restricted to the early stages of tumour development." (PMID 34680297, 2021). "This is carried out by the AR-expressing component of stroma and is therefore likely at least in non-reactive (non-tumor) stroma to be susceptible to the inhibitory effects of anti-androgens." (PMID 33477370, 2021). "We have previously reported on development of non-invasive fPSA-targeted radiotheranostics, including PET-based detection of metastatic disease, assessment of lesion specific AR-activity, and prostate-tumor-specific delivery of both alpha and beta radionuclides." (PMID 34298682, 2021). "AR-positive TNBC was shown to frequently have activating mutations in the phosphatidylinositol-4, 5-biphospate 3-kinase catalytic subunit alpha (PIK3CA) or pAKT, suggesting a tumor-promoting effect, but it was sensitive to combined inhibition by PI3K and AR." (PMID 34070471, 2021). "IHC data indicated that 60.6% of the tumors had a basal-like phenotype (i.e., a TNBC tumor that expresses at least one of the two basal markers, EGFR and CK5/6) and 36.5% of the tumors had a molecular apocrine phenotype (i.e., a TNBC tumor that expresses both AR and FOXA1)." (PMID 33673133, 2021). "In addition to the several “cis” mechanisms that cause gain-of-function mutations in the AR gene, it is now well established that the AR pathway can be stimulated within the tumours by the upregulation of androgen synthesis." (PMID 33993099, 2021). "Additionally, three AR aberrations (AR T878A, AR-V7 and wild-type AR amplification) have been recently identified in enriched-tumor exosomes from a small cohort of CRPC patients." (PMID 34772427, 2021). "Recent studies also indicated that AR might play positive roles to promote tumor cell proliferation in both PCa and BCa cells." (PMID 34127806, 2021). "However, preclinical data suggest that AR plays a differential role in tumor suppression and oncogenesis within ER+ and ER− breast tissue, respectively." (PMID 33591468, 2021). "It was described that in fibroblasts which are adjacent to tumor tissue, AR expression may decrease, thus leading to increased expression of IL-8 and the CC-chemokine ligand 2 (CCL2) and stimulation of migration and invasion." (PMID 34204596, 2021). "Thus, using agents to target androgen and its receptor AR lack the effectivity for castration‐resistant PCa and render the tumor to develop resistance to anti‐androgen‐related therapies." (PMID 33275817, 2021). "Recent data suggest that DPP4 may act as a tumor suppressor gene to the AR pathway, and that DPP4 inhibition can result in emergence of resistance to ADT." (PMID 34055551, 2021). "We designed rescue experiments using miRNA-130a-3p inhibitor to verify whether LINC00667 can promote tumor via LINC00667/miRNA-130a-3p/AR axis." (PMID 34907204, 2021). "Since PCa tumor growth is primarily driven by androgen receptor (AR) signaling, treatments include the use of drugs that decrease androgen synthesis or block binding of androgens to AR, called androgen deprivation therapy (ADT)." (PMID 34884984, 2021).
tumor (continued). "The SID-IP-LC-MS method in combination with endoproteinase Glu-C (V8 protease) digestion could be used in the future to specifically quantify AR-FL together with all the AR-SVs in tumor tissues and CTCs." (PMID 33384381, 2021). "Disruption of the AR interaction with coactivators such as the BET bromodomain family protein, the BRD4 methyltransferase complex, and the MLL-Menin, DNA repair enzymes—DNA-PKcs, have shown promising results in attenuating AR signaling and tumor growth in CRPC." (PMID 33384381, 2021). "We are currently conducting further experiments including overexpression of c-Myc in GBM cell lines to potentially overcome the effects from AR suppression, as well as CRISPR/CAS9-mediated AR knockout in GBM cell lines to investigate the multi-faceted functions of AR in GBM tumor growth." (PMID 34094902, 2021). "Thus, potent suppression of AR signaling promotes the development of a variety of castration-resistant tumor subtypes, ranging from tumors that remain positive for AR-dependent PC and NEPC to DNPC." (PMID 33921329, 2021). "FOXO 1 is a tumor suppressor which binds directly to the AR." (PMID 33919565, 2021). "Here we found ASC-J9® could also suppress the PCa progression via an AR-independent mechanism, which might involve modulating the tumor suppressor ATF3 expression." (PMID 33390173, 2021). "This metabolite has been noted to stimulate AR and promote tumor progression in animal models." (PMID 34830878, 2021). "In many cancers, the expression of AR is related to tumor stage." (PMID 34440475, 2021). "In contrast, three studies showed that lack of tumor AR expression was strongly associated (odds ratio, 0.41) with more frequent UBC recurrence, although discordant results have been reported." (PMID 34768683, 2021). "Likewise, antagonizing AR function in combination with CDK4/6 inhibition (abemaciclib) suppresses TNBC tumor growth, the direct opposite of that observed for luminal disease where AR agonism synergized with CDK4/6 inhibition (palbociclib) to block growth." (PMID 34680352, 2021). "Additionally, in cooperation with other TFs, FOXA1 facilitates the oncogenic switch of AR signalling, yet its expression has a tumour-suppressive impact on the progression of primary PCa to NEPC." (PMID 34940756, 2021). "Simultaneously, MYST1 interacts with p65 and androgen receptor (AR) to regulate tumor behavior." (PMID 34769241, 2021). "A negative association between AR expression and tumour stage has been reported before, both at the mRNA and protein levels." (PMID 33797847, 2021). "Furthermore, our in vitro study indicated three factors particularly relevant in contributing to the downregulation of AR-mediated pathways: exposure to androgen, hypoxia state of the tumor environment, and interaction with immune cells." (PMID 33808801, 2021). "Moreover, stimulating AR signalling by testosterone was able to counteract docetaxel induced long-term tumour regression, demonstrating that AR signalling directly contributed to taxane resistance." (PMID 34749299, 2021). "Multiple lines of evidence indicate that the CAF-secreted IL-6 may also influence tumor growth by affecting AR activity." (PMID 33535458, 2021). "Arguing against this hypothesis are the published data showing that knocking down of AR by siRNA resulted in significant inhibitory effects on GBM cell growth in vitro although whether the effects were mainly on differentiated tumor cells or CSCs is unclear." (PMID 34094902, 2021). "The detection of one such variant (i.e., AR splice variant Arv7) in circulating tumor cells or in peripheral whole blood, without the need for CTC capture, can predict poor response to abiraterone and enzalutamide, i.e., second-generation AR antagonists." (PMID 34298683, 2021). "Direct transcriptional regulation of SDH enzyme by AR may impart privileged control of energetics necessary for AR‐driven tumor progression." (PMID 33709547, 2021).